RNU6-668P (RNA, U6 small nuclear 668, pseudogene)
Gene: Small nuclear RNA gene on chromosome 4 (164,787,290 to 164,787,396, forward strand). Ensembl gene ENSG00000201050.
Homologues: Orthologues: chimpanzee U6 (99% identical), macaque U6 (93% identical). Paralogues in human: RNU6-727P (89% identical), RNU6-797P (88% identical), RNU6-1287P (86% identical), RNU6-1091P (85% identical), RNU6-1094P (85% identical), RNU6-1249P (85% identical), RNU6-43P (85% identical), RNU6-884P (85% identical), RNU6-1083P (84% identical), RNU6-175P (84% identical), RNU6-26P (84% identical), RNU6-272P (84% identical), and 1285 more.